U6 (U6 spliceosomal RNA )
Synonyms: LOC124904706
Gene: Small nuclear RNA gene on chromosome 1 (516,376 to 516,479, reverse strand). Ensembl gene ENSG00000278757.
Gene Ontology:
Molecular function: U4 snRNA binding
Biological process: formation of quadruple SL/U4/U5/U6 snRNP; spliceosomal tri-snRNP complex assembly
Cellular component: U4/U6 x U5 tri-snRNP complex; U6 snRNP
Homologues: Orthologues: macaque U6 (91% identical), pig U6 (84% identical), pig U6 (78% identical), dog U6 (77% identical). Paralogues in human: RNU6-1076P (100% identical), RNU6-1100P (100% identical), RNU6-1118P (100% identical), RNU6-1217P (100% identical), RNU6-355P (100% identical), RNU6-447P (100% identical), RNU6-785P (100% identical), RNU6-791P (100% identical), RNU6-860P (100% identical), U6 (100% identical), RNU6-1054P (99% identical), RNU6-1199P (99% identical), and 1290 more.